IGF1R (insulin like growth factor 1 receptor)
Description:
Receptor tyrosine kinase which mediates actions of insulin-like growth factor 1 (IGF1). Binds IGF1 with high affinity and IGF2 and insulin (INS) with a lower affinity. The activated IGF1R is involved in cell growth and survival control. IGF1R is crucial for tumor transformation and survival of malignant cell. Ligand binding activates the receptor kinase, leading to receptor autophosphorylation, and tyrosines phosphorylation of multiple substrates, that function as signaling adapter proteins including, the insulin-receptor substrates (IRS1/2), Shc and 14-3-3 proteins. Phosphorylation of IRSs proteins lead to the activation of two main signaling pathways: the PI3K-AKT/PKB pathway and the Ras-MAPK pathway. The result of activating the MAPK pathway is increased cellular proliferation, whereas activating the PI3K pathway inhibits apoptosis and stimulates protein synthesis. Phosphorylated IRS1 can activate the 85 kDa regulatory subunit of PI3K (PIK3R1), leading to activation of several downstream substrates, including protein AKT/PKB. AKT phosphorylation, in turn, enhances protein synthesis through mTOR activation and triggers the antiapoptotic effects of IGFIR through phosphorylation and inactivation of BAD. In parallel to PI3K-driven signaling, recruitment of Grb2/SOS by phosphorylated IRS1 or Shc leads to recruitment of Ras and activation of the ras-MAPK pathway. In addition to these two main signaling pathways IGF1R signals also through the Janus kinase/signal transducer and activator of transcription pathway (JAK/STAT). Phosphorylation of JAK proteins can lead to phosphorylation/activation of signal transducers and activators of transcription (STAT) proteins. In particular activation of STAT3, may be essential for the transforming activity of IGF1R. The JAK/STAT pathway activates gene transcription and may be responsible for the transforming activity. JNK kinases can also be activated by the IGF1R. IGF1 exerts inhibiting activities on JNK activation via phosphorylation and inhibition of MAP3K5/ASK1, which is able to directly associate with the IGF1R. When present in a hybrid receptor with INSR, binds IGF1. PubMed:12138094 shows that hybrid receptors composed of IGF1R and INSR isoform Long are activated with a high affinity by IGF1, with low affinity by IGF2 and not significantly activated by insulin, and that hybrid receptors composed of IGF1R and INSR isoform Short are activated by IGF1, IGF2 and insulin. In contrast, PubMed:16831875 shows that hybrid receptors composed of IGF1R and INSR isoform Long and hybrid receptors composed of IGF1R and INSR isoform Short have similar binding characteristics, both bind IGF1 and have a low affinity for insulin.
Synonyms: CD221; JTK13; IGFIR; MGC18216; IGFR
Tractability: Small molecule: an approved drug acts on it; a structure with a bound ligand is known; a high-quality ligand is known; it has a high-quality binding pocket; it belongs to a druggable protein family. Antibody: an approved drug acts on it; UniProt places it where antibodies can reach, with high confidence; its Gene Ontology location is reachable by antibodies, with high confidence; UniProt predicts a signal peptide or a membrane-spanning region. PROTAC: it is named in the literature on targeted protein degradation; UniProt records ubiquitination sites on it; ubiquitination databases record sites on it; its protein half-life has been measured; a small molecule that binds it is known. Other modalities: an approved drug acts on it.
Target class: Enzyme; Tyrosine protein kinase InsR family; TK protein kinase group; Kinase; Protein Kinase
Chemical probes: NVP-AEW541 (high quality), PD085407, linsitinib (high quality)
Gene: Protein-coding gene on chromosome 15 (98,648,539 to 98,964,530, forward strand). Ensembl gene ENSG00000140443.
Subcellular location: Cell membrane
Subcellular location (Human Protein Atlas): Nucleoli; Plasma membrane; Nucleoli rim; Primary cilium
Pathways (Reactome):
Signal Transduction: Extra-nuclear estrogen signaling; IRS-related events triggered by IGF1R; SHC-related events triggered by IGF1R; Signaling by Type 1 Insulin-like Growth Factor 1 Receptor (IGF1R)
Disease: Respiratory syncytial virus (RSV) attachment and entry
Gene Ontology:
Molecular function: identical protein binding; insulin binding; insulin receptor binding; insulin receptor substrate binding; insulin-like growth factor binding; insulin-like growth factor I binding; insulin-like growth factor receptor activity; phosphatidylinositol 3-kinase binding; protein binding; protein tyrosine kinase activity; insulin receptor activity; ATP binding; protein kinase activity; transmembrane receptor protein tyrosine kinase activity
Biological process: amyloid-beta clearance; cellular response to amyloid-beta; immune response; insulin-like growth factor receptor signaling pathway; negative regulation of apoptotic process; negative regulation of MAPK cascade; peptidyl-tyrosine autophosphorylation; positive regulation of cell migration; positive regulation of cell population proliferation; positive regulation of phosphatidylinositol 3-kinase/protein kinase B signal transduction; protein autophosphorylation; regulation of JNK cascade; transcytosis; cellular response to glucose stimulus; dendritic spine maintenance; insulin receptor signaling pathway; phosphatidylinositol 3-kinase/protein kinase B signal transduction; positive regulation of cold-induced thermogenesis; positive regulation of MAPK cascade; positive regulation of protein-containing complex disassembly; signal transduction; cell surface receptor protein tyrosine kinase signaling pathway; cellular response to oxygen-containing compound
Cellular component: alphav-beta3 integrin-IGF-1-IGF1R complex; membrane; plasma membrane; protein kinase complex; receptor complex; axon; insulin receptor complex
Genetic constraint (gnomAD): Loss-of-function variants: 44 observed, 143.91 expected, observed/expected ratio (o/e) 0.31, 90% interval 0.24 to 0.39. The upper end of that interval is the gene's LOEUF score, 0.39, which puts it in group 1 of 6, group 1 being the genes least tolerant of losing a copy. Missense variants: 1,345 observed, 1,901.3 expected, observed/expected ratio (o/e) 0.71, 90% interval 0.68 to 0.74. Synonymous variants: 794 observed, 751.48 expected, observed/expected ratio (o/e) 1.06, 90% interval 1 to 1.12.
Homologues: Orthologues: chimpanzee IGF1R (99% identical), macaque IGF1R (99% identical), pig IGF1R (98% identical), guinea pig IGF1R (97% identical), dog IGF1R (97% identical), mouse Igf1r (96% identical), rat Igf1r (96% identical), rabbit IGF1R (93% identical), tropical clawed frog igf1r (76% identical), zebrafish igf1ra (68% identical), zebrafish igf1rb (65% identical). Paralogues in human: INSR (58% identical), INSRR (53% identical), ROS1 (18% identical), ALK (16% identical), MET (15% identical), NTRK3 (15% identical), EPHA3 (15% identical), EPHB3 (15% identical), EPHA6 (15% identical), ERBB2 (15% identical), NTRK1 (15% identical), NTRK2 (15% identical), and 41 more.
Diseases named in the same sentence as IGF1R in open-access papers:
IGF1R is named in the same sentence as 589 diseases in open-access papers, as found by Europe PMC text mining. Sharing a sentence is not in itself a finding about the gene and the disease. The quoted sentences say what the papers report.
breast cancer (720 papers, 1996 to 2026). A primary or metastatic malignant neoplasm involving the breast. "The Insulin-Like Growth Factor 1 Receptor (IGF-1R) signaling pathway is a tightly regulated network critical for cell proliferation and has been implicated as an oncogenic driver in breast cancer, sarcoma, and NSCLC." (PMID 38254905, 2024). "Similar studies have been performed in breast cancer, where the IGFs/IGF-1R axis causes activation of breast epithelial malignant cells and conversion of stromal fibroblasts to CAFs, and it promotes TME remodeling for tumor invasion." (PMID 38887298, 2024). "Clinical investigation also revealed that CXCL1 was an independent risk factor for breast cancer prognosis and positively correlated with IGF1R and HMGB1 expression." (PMID 39394189, 2024). "A similar association between nuclear IGF-1R and worse outcomes has been reported in osteosarcomas, pediatric gliomas, synovial sarcomas, breast cancer, clear cell renal cell carcinoma, and embryonal rhabdomyosarcoma." (PMID 37858153, 2023). "This study shows that the presence of IGF1R SNVs rs3743259 and rs3743258 is associated with worse pathological response compared to the reference genotype in this cohort of patients with breast cancer treated with neoadjuvant chemotherapy." (PMID 38136416, 2023). "The phosphorylation of RPS6 is a marker for the activation of the IGF1R/PI3K/AKT/mTORC1 pathway associated with resistance to therapy in breast cancer." (PMID 37686596, 2023). "Insulin-like growth factor receptor 1 (IGF1R) and its signalling has been extensively studied in breast cancer and it has been implicated in resistance to hormone therapies, HER2 targeted therapies, and chemotherapy." (PMID 36920947, 2023). "Human breast and mouse mammary tumors with reduced IGF1R are associated with upregulation of several pathways necessary for promoting metastasis supporting the conclusion that IGF1R normally helps maintain a metastasis suppressive tumor microenvironment." (PMID 36568144, 2022). "IGF-1R phosphorylation is observed across all breast cancer subtypes and is associated with poor patient survival." (PMID 36556357, 2022). "Although the insulin-like growth factor 1 receptor (IGF1R) has been considered a target for inhibition in breast cancer, low levels of IGF1R expression are associated with worse overall patient survival." (PMID 36568144, 2022). "As with total IGF-1R, associations between cytoplasmic IGF-1R localization and breast cancer prognosis are subtype dependent." (PMID 36556357, 2022). "IGF-1R nuclear translocation is closely associated with cell proliferation in multiple breast cancer cell lines and inhibiting IGF-1R nuclear localization reduces cell proliferation and migration in both non-malignant mammary cells and breast carcinoma cells." (PMID 36556357, 2022). "Here, we propose a novel mechanism that oncogenic protein TRIP-Br1 renders breast cancer cells and insulin deficient mice to have higher IR/IGF1R ratio by positively and negatively regulating IR and IGF1R expression at the protein level, respectively." (PMID 35710446, 2022). "IGF-1R signal pathway is highly associated with resistance to the EGFR inhibitors in breast cancer cells." (PMID 35399718, 2022). "One additional module significantly associated with high IGF1R (correlation 0.61) was also associated with ER+/PR+ breast cancers and low tumor grade." (PMID 36568144, 2022). "Taken together, it is clear that loss of IGF1R in mammary tumors alters the microenvironment to promote metastasis." (PMID 36568144, 2022). "IGF-1R expression is only associated with prognosis in some breast cancer subtypes and the impact on outcome is varied." (PMID 36556357, 2022). "Although a lot of the evidence is based on cell models they did find that p-IGF-1R/IR positivity in ER+ breast cancer is associated with reduced benefit from adjuvant tamoxifen in postmenopausal patients." (PMID 33816477, 2021).
breast cancer (continued). "We experimentally validate our model’s predictions in three breast cancer cell lines, leading to possible new targets for IGF1R-associated cancer therapy." (PMID 34191793, 2021). "In the IGF-1R 3+ MCF7 breast cancer model, treatment with 3 mg/kg W0101 was shown to cause 90% tumor growth inhibition (TGI)." (PMID 34203870, 2021). "The type I insulin-like growth factor receptor (IGF-1R) has been implicated in breast cancer growth, proliferation, and survival." (PMID 34611148, 2021). "Insulin receptor is a known signaling pathway in breast cancer and it has been suggested that insulin receptor activation results in a kinome signature distinct from IGF-1R and also associated with poor outcome." (PMID 34611148, 2021). "Our data suggest that loss of IGF-1R expression renders endocrine-resistant breast cancer cells more sensitive to insulin, probably due to increased insulin binding sites, which activates the overlapping pro-tumorigenic pathways to IGF-1R." (PMID 33429867, 2021). "IGF-1R overexpression is associated with decreased breast cancer survival, increases in recurrence, and treatment resistance to radiation and Herceptin, which are both used to treat brain metastases." (PMID 35008602, 2021). "Elevated levels of insulin-like growth factor 1 (IGF1) and excessive IGF1R signaling have been implicated in an increased risk of breast cancer." (PMID 34441794, 2021). "IGF/IGF1R signaling is implicated in cancer cell colonization, survival, and proliferation in bone for multiple cancers, including neuroblastoma, PCa, and breast cancer." (PMID 34185427, 2021). "SNPs rs2229765 and rs8038415 in IGF1R had been linked to several cancer types, including colorectal cancer, breast cancer, papillary thyroid carcinoma, and non-small cell lung cancer." (PMID 32150843, 2020). "By analyzing the public online database, high expression level of IGF1R (probe: 225330_at and 243358_at) was associated with poor OS in patients with breast cancer, which was consisted with the previously reported study." (PMID 32194644, 2020). "Alterations in the IGF-1/IGF-1R-mediated signaling have been associated with the development and progression of hormone-related tumors, including breast cancer." (PMID 32325700, 2020). "In this context, it has been shown that active IGF-1R can be found overexpressed in all subtypes of breast cancer, and that the presence of high levels of phosphorylated IGF-1R is associated with a lower patient survival." (PMID 33322337, 2020). "Experiments in ER+ breast cancer cell lines demonstrate that activation of the IGF‐1R signaling pathway is associated with PI3K/MAPK pathway signaling, p‐ERα(Ser167) phosphorylation and cell proliferation in the presence of tamoxifen." (PMID 31490549, 2020). "In Wnt-driven tumors, the inhibition of IGF-1R signaling led to increased mammary tumor development, potentially through a loss of protection from cellular stress and the development of a pro-metastatic tumor microenvironment." (PMID 33604295, 2020). "In conclusion, p‐IGF‐1R/InsR positivity in ER+ breast cancer is associated with reduced benefit from adjuvant tamoxifen in postmenopausal patients." (PMID 31490549, 2020). "The miRNA-mRNA network shows that significantly deregulated miRNAs in the FS and FSO groups target genes involved in the MG development (red circles) and/or associated with breast cancer (blue circles), including Egfr, Igf-1, Igf-1R, Hif1a, Ets1, and pgr." (PMID 31689992, 2019). "The expression of the insulin-like growth factor 1 (IGF-1R) is assumed to be linked with the overall survival of breast cancer patients." (PMID 31652624, 2019). "The IGF family members, together with the IGF1R, were found to be overexpressed in breast cancer tumors and associated with cancer progression." (PMID 31064156, 2019). "Consistently, expression of IGF-1R is up-regulated by E2 through ERα but downregulated by tamoxifen, which leads to the loss of IGF-1R in the tamoxifen resistant breast cancer." (PMID 31815253, 2019).
breast cancer (continued). "In contrast, among those women who ultimately develop breast cancer, inheriting the IGF1R expression blunting effect of the rs2016347 T allele confers a greater clinical response rate to neoadjuvant chemotherapy and a better overall survival outcome." (PMID 31687025, 2019). "By itself, higher expression of IGF1R in TDLUs can increase later-life risk of developing breast cancer by nearly 16-fold." (PMID 31687025, 2019). "Recent studies have shown that particular IGF1R polymorphisms significantly increase the risk of early tumor progression in tamoxifen-treated ER+ breast cancer, and that inhibition of IGF1R activity enhances response to trastuzumab therapy." (PMID 29796176, 2018). "As expected, IGF1R deficiency was able to significantly increase breast cancer cell sensitivity to lapatinib in a three-day dose-response assay; however, among the newly identified genes, only TALDO1 depletion conferred similar sensitivity in this assay." (PMID 30323337, 2018). "In patients with breast cancer, markers of aggressiveness such as dysregulation of the insulin‐like growth factor receptor (IGF1R) system and E‐cadherin loss are commonly observed." (PMID 28766847, 2018). "Our analysis of the Molecular Taxonomy of Breast Cancer International Consortium (METABRIC) dataset revealed association between low IGF-1R and reduced overall patient survival." (PMID 30458886, 2018). "In contrast, ER-α shows the moderately active protein (represented by ++) compared to wet-lab experiments which means that there is a crosstalk between IGF-1R and ER-α, associated with an increased risk of breast cancer metastasis." (PMID 29787591, 2018). "Based upon our data, we constructed a resultant mechanism of IGF-1R associated breast cancer cellular pathway by which targeted growth factors to overcome endocrine therapy resistance." (PMID 29787591, 2018). "(2002) showed that reduced expression of IGF1R in MCF‐7 breast cancer cells was associated with decreased expression of E‐cadherin and increased cell motility." (PMID 28766847, 2018). "PN is a graph theoretical approach, which has been successfully implemented for the models and analysis of homeostatic/pathological response of IGF-1R associated network with breast cancer." (PMID 29787591, 2018). "Previous in vivo and in vitro studies have linked higher levels of IGF-1R and its ligands with various types of cancer development and progression including breast cancer, prostate cancer, myeloma and colon cancer." (PMID 29787591, 2018). "Our model has predicted that deregulation of IGF-1R associated signaling pathway should be controlled by the inhibition of multiple targets in order to treat breast cancer." (PMID 29787591, 2018). "We found that phenformin significantly inhibits proliferation, migration, invasion, and EMT in ErbB2-overexpressing breast cancer cells and blocks tumor growth in a syngeneic mammary tumor model, which were associated with the inhibition of IGF1R stimulation." (PMID 28947975, 2017). "The growth-promoting effects of IGF-1 are mediated primarily through IGF1R, and high cytoplasmic expression of IGF1R in terminal duct lobular units (TDLUs) has been associated with significantly increased risk of later-life breast cancer." (PMID 28822014, 2017). "In the Marin Women’s Study, pregnancy-induced hypertension was shown to interact with the T allele of a functional IGF1R gene variant, rs2016347, to result in lower breast density, as well as decreased breast cancer risk." (PMID 28822014, 2017). "The expression patterns of IGF1R, InsR and pIGF1R are therefore important to elucidate in this complex network, its involvement in breast cancer, and its association with prognosis in different treatment groups." (PMID 28030849, 2017). "Overexpression of igf1r gene is implicated in cellular proliferation, transformation, and metastasis in several carcinomas, including breast cancer." (PMID 29119846, 2017).